SDK1 (sidekick cell adhesion molecule 1)
Description:
Adhesion molecule that promotes lamina-specific synaptic connections in the retina. Expressed in specific subsets of interneurons and retinal ganglion cells (RGCs) and promotes synaptic connectivity via homophilic interactions.
Synonyms: FLJ31425
Tractability: Antibody: its Gene Ontology location is reachable by antibodies, with high confidence; UniProt places it where antibodies can reach, with medium confidence; UniProt predicts a signal peptide or a membrane-spanning region. PROTAC: its protein half-life has been measured.
Gene: Protein-coding gene on chromosome 7 (3,301,252 to 4,269,000, forward strand). Ensembl gene ENSG00000146555.
Subcellular location: Cell membrane; Synapse
Subcellular location (Human Protein Atlas): Cytosol
Pathways (Reactome):
Cell-Cell communication: SDK interactions
Gene Ontology:
Molecular function: identical protein binding
Biological process: homophilic cell-cell adhesion; retina layer formation; synapse assembly
Cellular component: plasma membrane; synapse
Genetic constraint (gnomAD): Loss-of-function variants: 140 observed, 209.5 expected, observed/expected ratio (o/e) 0.67, 90% interval 0.58 to 0.77. The synonymous counts are far from expectation, so gnomAD's model fits this gene poorly and the ratio says little. Missense variants: 3,328 observed, 2,819.6 expected, observed/expected ratio (o/e) 1.18, 90% interval 1.15 to 1.22. Synonymous variants: 1,517 observed, 1,202 expected, observed/expected ratio (o/e) 1.26, 90% interval 1.21 to 1.32.
Homologues: Orthologues: macaque SDK1 (98% identical), mouse Sdk1 (90% identical), rat Sdk1 (89% identical), chimpanzee SDK1 (88% identical), guinea pig SDK1 (87% identical), dog SDK1 (85% identical), pig SDK1 (80% identical), zebrafish sdk1a (66% identical). Paralogues in human: SDK2 (58% identical), IGSF10 (13% identical), ROBO1 (13% identical), MXRA5 (13% identical), HMCN2 (12% identical), NEO1 (12% identical), DCC (12% identical), PTPRQ (12% identical), ROBO2 (11% identical), IGDCC4 (11% identical), ROBO3 (11% identical), DSCAML1 (10% identical), and 24 more.
Diseases named in the same sentence as SDK1 in open-access papers:
SDK1 is named in the same sentence as 41 diseases in open-access papers, as found by Europe PMC text mining. Sharing a sentence is not in itself a finding about the gene and the disease. The quoted sentences say what the papers report.
breast carcinoma (5 papers, 2019 to 2023). "Among the candidate CpGDMs, we found eight genes with differential methylation previously associated with breast cancer susceptibility and pathology in the G2SBC and COSMIC Databases (AMOTL1, CDCP1, CYFIP1, MAP3K6, MIB2, SDK1, TAL1, and TYROBP)." (PMID 33145876, 2021). "Importantly, increases in COL8A1, BGN, COL11A1, POSTN, MMP11 and SORCS2 and decreased LTBP4, PCOLCE2, LRRC17 and SDK1 have been identified in CAS and CAFs from human breast cancer and are consistently perturbed in stroma of canine and human mammary cancer." (PMID 37391533, 2023).
Hypertension (5 papers, 2016 to 2024). The presence of chronic increased pressure in the systemic arterial system. "We also observed an association with SDK1 gene, which has been previous linked with hypertension in Nigerian and Japanese populations)." (PMID 41542229, 2024). "Of those, 28 genes had more than 5 var-HpaII sites, and several of those have been reported the association with PE (PTPRN2, KCNMA1, and NFATC1), hypertension (SDK1), and placental development (SALL3)." (PMID 27293492, 2016). "The LMM GWAS for HCM reached suggestive significance (P = 2.76 × 10−7) with a marker on chromosome E3, located within the gene SDK1 (sidekick cell adhesion molecule 1), which is expressed especially in the kidney and retina but has also been associated with hypertension." (PMID 35782544, 2022). "SDK1 was found to be associated with hypertension in the Japanese population." (PMID 28710368, 2017). "Lastly, the SDK1 gene has particular interest because of its link with hypertension in two prior GWAS in Nigerians and Japanese populations." (PMID 41542229, 2024).
prostate carcinoma (4 papers, 2017 to 2022). A carcinoma that arises from epithelial cells of the prostate gland. "A causal relationship between this SDK1:AMACR fusion and prostate cancer progression remains to be clarified." (PMID 32982686, 2020). "SDK1 is an androgen-responsive gene and its overexpression modulates cellular migration in prostate cancer." (PMID 31639042, 2019). "Finally, in some prostate cancer patients, gene fusions of SDK1 to AMACR (a-methylacyl-CoA racemase gene) and its transcript have been previously observed." (PMID 32982686, 2020). "The original prostate cancer study indicated that the 14 prostate cancer samples harbored 38 tumor-specific chimeric transcripts, of which at least 5 are recurrent transcripts in Chinese population, including TMPRSS2-ERG, USP9Y-TTTY15, CTAGE5-KHDRBS3, RAD50-PDLIM4, and SDK1-AMACR." (PMID 29181411, 2017).
colorectal cancer (2 papers, 2022 to 2025). A primary or metastatic malignant neoplasm that affects the colon or rectum. "Sidekick cell adhesion molecule 1 (SDK1) hypomethylation was also reported in sporadic colorectal cancer and is concordant with our findings." (PMID 35054365, 2022). "Specifically, the top two genes specific to MCP were colorectal cancer suppressor (DCC) and sidekick cell adhesion molecule 1 (SDK1), which were enriched in subcortical limbic regions and were involved in mechanisms related to axonogenesis." (PMID 40173244, 2025).
depression (2 papers, 2020 to 2023). "Additionally, we identified significant methylation sites in individual genes that have been previously linked to neuropsychiatric disorders, including depressive disorders (FAM172A), internalizing disorders (SDK1), and neurodegenerative disorders (PRR7)." (PMID 37634000, 2023). "Experimental animal studies have also pinpointed that Sdk1-mediated neural circuits may be responsible for addiction and depression." (PMID 32982686, 2020).
lung adenocarcinoma (2 papers, 2017 to 2022). A carcinoma that arises from the lung and is characterized by the presence of malignant glandular epithelial cells. "SDK1 has been shown to be overexpressed in asbestos-induced lung adenocarcinoma, Sdk1 is also expressed in retinal synaptic sites and may be dangerous for this reason." (PMID 28871274, 2017).
Obesity (2 papers, 2021 to 2025). Accumulation of substantial excess body fat. "No role in regulating metabolism or obesity has been discovered previously for either calpA/CAPN8 or sdk/SDK1." (PMID 34748544, 2021).
schizophrenia (2 papers, 2015 to 2019). A major psychotic disorder characterized by abnormalities in the perception or expression of reality. "Copy number variations in SDK1, among several other genes, have been associated with schizophrenia in the Asian population." (PMID 30600573, 2019). "In the candidate CNV regions, 26 regions had no overlaps with the common CNVs found in Asian populations and included the genes (i.e., ANTXRL, CHST9, DNM3, NDST3, SDK1, STRC, SKY) that are associated with schizophrenia and/or other psychiatric diseases." (PMID 26136833, 2015). "SDK1 and SKY are the genes whose expression levels are markedly altered in the brain of schizophrenia patients." (PMID 26136833, 2015).
aneurysm (1 paper, 2021). Bulging or ballooning in an area of an artery secondary to arterial wall weakening. "Upon studying these genes for a possible role in MFS, four genes (FNBP1, EHBP1, SDK1, and PTPRN2) were found to be involved in cytoskeletal actin dynamics, which regulates cell-adhesion and cellular uptake or secretion, which is altered in MFS cells, and thought to play a role in aneurysm formation." (PMID 34895303, 2021).
Anxiety (1 paper, 2022). Intense feelings of nervousness, tension, or panic often arise in response to interpersonal stresses. "Overexpression of the gene sidekick cell adhesion molecule 1 (Sdk1), in the vHPC also promoted depressive and anxiety-like behavioral features to social stress." (PMID 35592639, 2022).
anxiety disorder (1 paper, 2023). A category of psychiatric disorders which are characterized by anxious feelings or fear often accompanied by physical symptoms associated with anxiety. "SDK1 mutations have been associated with anxiety disorders, and blood methylation levels in SDK1 have been associated with different forms of psychopathology." (PMID 37634000, 2023).
asthma (1 paper, 2024). "In addition, our MAGMA analyses implicated another four pleiotropic genes—RERG, RBM6, SDK1, and HLA-B as potential targets for further investigation into asthma and GERD." (PMID 39223263, 2024). "After comparison, asthma and GERD were found to share six genes (ERBB3, RBM6, HLA-B, SDK1, RERG, RAB5B), one of which, ERBB3, was also significantly associated with both eczema and GERD." (PMID 39223263, 2024).
COVID-19 (1 paper, 2022). A disease caused by infection with severe acute respiratory syndrome coronavirus 2. "We identified 230 LUAD/COVID-19 DEGs and constructed a risk score containing 7 genes (BTK, CCL20, FURIN, LDHA, TRPA1, ZIC5, and SDK1) that could classify LUAD patients into two risk groups." (PMID 35733175, 2022). "The analyses of these 7 gene expression levels between different clinical features suggested that BTK, SDK1, CCL20, LDHA, and ZIC5 may serve as effective biomarkers for screening and characterizing patients with LUAD/COVID-19 at different stages." (PMID 35733175, 2022).
glioma (1 paper, 2026). A benign or malignant brain and spinal cord tumor that arises from glial cells (astrocytes, oligodendrocytes, ependymal cells). "SDK1 is a candidate prognostic biomarker in glioma co-occurring with ECM remodeling and immunosuppressive features, warranting experimental validation for clinical translation." (PMID 42196180, 2026). "Sidekick Cell Adhesion Molecule 1 (SDK1), an immunoglobulin superfamily member mediating homophilic adhesion, has been documented in glioma tissue but lacks systematic prognostic evaluation." (PMID 42196180, 2026).
glomerulosclerosis (1 paper, 2013). A hardening of the kidney glomerulus caused by scarring of the blood vessels. "SDK1 causes dedifferentiation of podocytes and induces their uncontrolled proliferation leading to glomerulosclerosis and nephropathy." (PMID 23593167, 2013).
Hepatic fibrosis (1 paper, 2024). The presence of excessive fibrous connective tissue in the liver. "Among these, the mRNA levels of nine genes, including USB1, NT5E, RORA, SDK1, and IL10, were significantly up-regulated, suggesting their involvement in the miRNA-30-mediated regulation of host hepatic fibrosis." (PMID 39139565, 2024).
hepatocellular carcinoma (1 paper, 2020). A malignant tumor that arises from hepatocytes. "An epigenomic study identified SDK1 as an epigenomic driver in hepatocellular carcinoma." (PMID 32617189, 2020).
insomnia (1 paper, 2024). A sleep disorder characterized by difficulty in falling asleep and/or remaining asleep. "In the realm of sleep and circadian health, reported genetic associations corroborated the relevance of EFNA5, ZNF521, WWOX, ALG10B, PAM and SDK1 with insomnia, daytime napping, or chronotype traits." (PMID 39070651, 2024).
kidney cancer (1 paper, 2024). Primary or metastatic malignant neoplasm involving the kidney. "SDK1 and SEMA5B implicated in prostate and kidney cancer, respectively, represent novel gene candidates with potential implications for understanding osteosarcoma heterogeneity." (PMID 39701601, 2024).
neuropathy (1 paper, 2016). A disorder affecting the nervous system that manifests with pain, tingling, numbness, and/or muscle weakness. "Inappropriate up-regulation of Sdk1 expression by podocytes has been linked to their dedifferentiation and loss of proper foot-process architecture, leading to collapsed glomeruli and neuropathy." (PMID 27644106, 2016). "Sdk1 has also been shown to be involved in the pathology of focal segmental glomerulosclerosis and HIV-associated neuropathy." (PMID 27644106, 2016).
pancreatic cancer (1 paper, 2024). "Overexpression of KIF11 and RCC1 and underexpression of ADCY1 and SDK1 were detected in ~ 60% of grade 2 pancreatic cancer patients and associated with ~ 60% mortality in stages I and II." (PMID 38741142, 2024). "In particular, the overexpression of KIF11 and RCC1 and the underexpression of ADCY1 and SDK1 were detected in ~ 60% of tumor grade 2 pancreatic cancer patients and associated with around 60% mortality in stages I and II, which shows they can be early-diagnosis markers for pancreatic cancer." (PMID 38741142, 2024). "The overexpression of KIF11 and RCC1 and the underexpression of ADCY1 and SDK1 were detected in ~ 60% of tumor grade 2 pancreatic cancer patients." (PMID 38741142, 2024). "KIAA1217, SLC44A1, INPP5B, and SDK1 were reversely correlated with some miRNAs not affecting patient survival, which shows these are potential therapeutic targets for pancreatic cancer." (PMID 38741142, 2024).
prostate tumor (1 paper, 2017). "Concerning CTAGE5-KHDRBS3, SDK1-AMACR, and RAD50-PDLIM4 gene fusions Ren proven their occurrence also in the additional 54 prostate tumor samples analysed (with percentages ranging from 24 to 37%)." (PMID 28114882, 2017).
Sepsis (1 paper, 2023). Sepsis is defined as life-threatening organ dysfunction caused by a dysregulated host response to infection. "Compared with sepsis, the three proteins with the largest decrease in HLH were protein sidekick-1 (SDK1), serum amyloid A-1 protein (SAA1), and C-reactive protein (CRP )." (PMID 37653176, 2023).
systemic lupus erythematosus (1 paper, 2024). An autoimmune multi-organ disease typically associated with vasculopathy and autoantibody production. "Notably, previous research has reported reduced SDK1 expression in the synovium of patients with systemic lupus erythematosus, suggesting its potential involvement in synovial disorder." (PMID 38092362, 2024).
viral infection (1 paper, 2025). "The results showed that SDK1 treatment attenuated the virus infection-induced interaction of MAP3K15 with Dorsal when total protein was used for IP assays." (PMID 40749022, 2025).
cancer (15 papers, 2013 to 2025). A tumor composed of atypical neoplastic, often pleomorphic cells that invade other tissues. "The gigantic Sdk1 gene is susceptible to erratic gene rearrangements or mutations in both somatic and germ-line cells, potentially contributing to neurological disorders and some types of cancers." (PMID 32982686, 2020). "The recurrent mutations suggest that Mtor and Sdk1 may also function as cancer drivers in NASH-HCC, while other recurrently mutated genes could represent novel candidates associated with NASH-HCC." (PMID 30367044, 2018). "Genes potentially associated with cell migration and cancer metastasis included CNTN5, FN1, Integrin Subunit Beta 6 (ITGB6), EPHB1, Unc-5 Netrin Receptor D (UNC5D), SDK1, RADIL, LRRC7, PCDH11X, and ADAMTS9." (PMID 39770638, 2024). "MAG proteins can make some combinations to improve cancer diagnosis and prognosis prediction, and SDK1 was the most combinable partner among them." (PMID 38741142, 2024). "Several mutated genes were identified in a murine NASH-associated HCC model, which has also been reported as drivers in other human cancers, including Mtor, Sdk1, Braf, Pik3cb, Ctnnd1, Ctnna3, Akt3, and Nos." (PMID 36612019, 2022). "SDK1 is a kind of immune-related protein, and studies found that SDK1 mutation causes cancers, but the effect of SDK1-related site methylation on the incidence of cancer has not been fully studied." (PMID 36060650, 2022). "SDK1 is a cell adhesion molecule that plays an active role in cancer development." (PMID 32617189, 2020). "A cross-species cancer study also suggested that SDK1 may be located in an unstable genomic region, while RE methylation itself is a strong regulator of genomic stability." (PMID 31639042, 2019). "SDK1 gene codes for a cell adhesion molecule with a potential role in cancer progression." (PMID 28514750, 2017). "For CNV deletions, only three genes (KCND2, SDK1, SP4) displayed more than three instances across different BD‐cancer patients." (PMID 39140252, 2025). "Chromosomal region 7p22 is located in a fragile sequence (FRA7B) containing two miRNA genes (mir589 and mir339) and three large genes (SDK1, THSD7A, MAD1L1), and is highly prone to gaps and breaks in several cancers." (PMID 23626673, 2013).
tumor (8 papers, 2017 to 2026). "The CNVs in C1 were mainly associated with tumor cell proliferation, such as the amplification of 5q31.3 (KCTD16) and 7p22.2 (SDK1), as well as the deletion of 4q24 (PPA2)." (PMID 34804944, 2021). "Further, this analysis identified SVs in a novel gene SDK1 in 5 out of the 20 ESCC tumor samples." (PMID 32617189, 2020). "Meanwhile, few genes were uniquely expressed in TERT altered tumours; amongst these were IRX3, SDK1 and TRIP13." (PMID 40097403, 2025). "Meanwhile, few genes were uniquely expressed in TERT-altered tumours but included IRX3, SDK1 and TRIP13." (PMID 38978571, 2024).
cardiovascular diseases (1 paper, 2021). "Seven of these DMPs (25%) could be allocated to a gene that was previously associated with cardiovascular diseases (HDAC4, IGF2BP3, CASZ1, SDK1, PCDHGA1, DIO3, PTPRN2)." (PMID 34895303, 2021).
kidney (1 paper, 2016). "Sdk1-associated kidney pathologies are thought to reflect a reversion of podocytes to the early developmental state, caused by inappropriate Sdk1 expression." (PMID 27644106, 2016).
SDK1 also shares sentences with these, for which no sentence is quoted: autism (1 paper); cervical cancer (1); cognitive decline (1); colorectal adenoma (1); eczema (1); infection (1); internalizing disorder (1); Nephropathy (1); neurological disorders (1); osteosarcoma (1); psychiatric diseases (1); urinary bladder cancer (1).